KRAS (KRas proto-oncogene, GTPase)
Diseases named in the same sentence as KRAS in open-access papers (continued):
Sharing a sentence is not in itself a finding about the gene and the disease.
metastatic colorectal cancer (continued). "While the predictive and prognostic significance of KRAS and BRAF mutations in metastatic colorectal cancer (mCRC) is well established, their impact on localized colorectal cancer (CRC) remains not fully elucidated." (PMID 39682117, 2024). "The objective of HERACLES cohort A was to examine the efficacy of dual HER2 blockade with trastuzumab plus lapatinib in patients with KRAS exon 2 wild-type metastatic colorectal cancer (mCRC) who exhibited HER2 amplifications and/or HER2 overexpression." (PMID 39682117, 2024). "In a study with 148 patients with metastatic colorectal cancer, it was found that after treating with FOLFOX, patients with KRAS mutations had worse PFS than wildtype patients." (PMID 37190303, 2023). "CD8+ T cells transfused with targeted mutant KRAS showed effective antitumor effects in KRAS G12D metastatic colorectal cancer, but were limited by HLA-C * 08:02." (PMID 37670322, 2023). "Approximately 50% of patients with metastatic colorectal cancer has mutations in the RAS gene, including HRAS, KRAS, and NRAS mutations, most of which are KRAS mutations." (PMID 37370699, 2023). "The aim of this study is to report the largest North African description of KRAS and NRAS status in metastatic colorectal cancer and to describe the association of these mutations with clinicopathological characteristics." (PMID 37277698, 2023). "The clinical benefits of this recognition were first realized in a case of metastatic colorectal cancer, which was successfully treated by adoptive T-cell therapy using ex vivo expanded tumor-derived lymphocytes that specifically recognized KRAS G12D." (PMID 37581538, 2023). "Using whole-genome analysis of 37 patients with metastatic colorectal cancer (mCRC) treated with the chemotherapy trifluridine/tipiracil (FTD/TPI), we identified KRAS codon G12 (KRASG12) mutations as a potential biomarker of resistance." (PMID 36864254, 2023). "The aim of the current study was to develop a mathematical model to quantitatively characterize the dynamics of treatment response and evolving resistance, based on tumor sizes and mutant KRAS levels in ctDNA from metastatic colorectal cancer (mCRC) patients." (PMID 35273301, 2022). "This study aimed to evaluate its safety, tolerability, pharmacokinetics (PK), and efficacy in patients with wild-type KRAS/NRAS/BRAF metastatic colorectal cancer (mCRC)." (PMID 36307775, 2022). "Cetuximab is an anti-epidermal growth factor receptor (EGFR) monoclonal antibody used as a single agent in patients with KRAS metastatic colorectal cancer, for which many patients acquire resistance." (PMID 35203305, 2022). "When the effect of anti-EGFR mAbs was analyzed in patients with metastatic colorectal cancer with wild-type KRAS only, clinically relevant response rates increased to approximately 60%." (PMID 35035479, 2022). "KRAS status serves as a predictive biomarker of response to treatment in metastatic colorectal cancer (mCRC)." (PMID 34108518, 2021). "FOLFIRI is also being tested with MEK162 to evaluate the response rate, clinical benefit and safety parameters in advanced KRAS positive metastatic colorectal cancers (Clinicaltrials.gov Identifier: NCT02613650 (accessed on 24 February 2021))." (PMID 33801965, 2021). "The results of our study suggested that, in the era of precision medicine, the possibility of KRAS discordance should be taken into account within the multidisciplinary management of patients with metastatic colorectal cancer." (PMID 33946899, 2021).
metastatic colorectal cancer (continued). "Cetuximab has been approved for use for first-line treatment of patients with wild-type KRAS metastatic colorectal cancer (CRC)." (PMID 33933132, 2021). "The data source was J-STEPP trial, which compared preemptive skin treatment with reactive treatment in third-line panitumumab therapy for KRAS wild type metastatic colorectal cancer in Japan." (PMID 34593037, 2021). "The case report of metastatic colorectal cancer patients discussed previously showed a primary response to KRAS-G12D targeted TILs." (PMID 34321091, 2021). "Whereas, in metastatic colorectal cancer, BRAF mutation seems to have the poorest prognosis compared with KRAS and NRAS." (PMID 34063325, 2021). "CD8+ T-cells against mutant KRAS G12D obtained from tumor-infiltrating lymphocytes (TILs) of a patient with metastatic colorectal cancer were reinfused at 1.11 × 1011 into the patient, resulting in regression of metastatic colon cancer after therapy." (PMID 35959968, 2021). "It provided further confirmation that patients with KRAS wild-type metastatic colorectal cancer (mCRC) were those most likely to benefit from cetuximab treatment." (PMID 33898421, 2021). "Results of our study suggested that, in the era of precision medicine, possibility of KRAS discordance should be taken into account within multidisciplinary management of patients with metastatic colorectal cancer." (PMID 33946899, 2021). "Oxaliplatin-based chemotherapy is more beneficial in KRAS mutant than in KRAS wild-type metastatic colorectal cancer." (PMID 33909629, 2021). "In the KRAS wild-type cohort, overall response rate (ORR) of 30% was reported; no significant responses were recorded in the KRAS mutated cohort of mCRC (metastatic colorectal cancer) patients." (PMID 32517369, 2020). "KRAS and BRAF mutations are prognostic and predictive tools in metastatic colorectal cancer, but little is known about their prognostic value in patients scheduled for cytoreductive surgery (CRS) and hyperthermic intraperitoneal chemotherapy (HIPEC)." (PMID 31571052, 2020). "We evaluated the ability of the fully-automated molecular diagnostics platform Idylla for the detection of KRAS, NRAS and BRAF hotspot mutations in plasma from patients with metastatic colorectal cancer (mCRC)." (PMID 31940389, 2020). "Cetuximab improves progression-free survival (PFS) and overall survival (OS) in patients with KRAS wild type (wt) metastatic colorectal cancer (mCRC)." (PMID 33347495, 2020). "Overall, these results suggest that KRAS mutant fragments in plasma can reflect the status of patients with metastatic colorectal cancer." (PMID 32379795, 2020). "The now clinically-used anti-epidermal growth factor receptor (EGFR) monoclonal antibodies have demonstrated significant efficacy only in patients with metastatic colorectal cancer (mCRC), with wild-type Kirsten rat sarcoma viral oncogene homolog (KRAS)." (PMID 32839411, 2020). "Mutations in KRAS, NRAS, and BRAF (RAS/BRAF) genes are the main predictive biomarkers for the response to anti-EGFR monoclonal antibodies (MAbs) targeted therapy in metastatic colorectal cancer (mCRC)." (PMID 32628708, 2020). "For example, T cells targeting mutant KRAS found in the endogenous TILs of a patient with KRAS-driven metastatic colorectal cancer showed minimal toxicity and all seven of the patient’s lesions initially regressed." (PMID 33569049, 2020). "Assessment of KRAS, NRAS (RAS) and BRAF mutations is a standard in the management of patients with metastatic colorectal cancer (mCRC)." (PMID 31265477, 2019). "A relevant role for NGS is the prediction of response to anti-EGFR agents in metastatic colorectal cancer (mCRC), where multiple exons from KRAS, NRAS, and BRAF must be sequenced simultaneously." (PMID 31036005, 2019).
metastatic colorectal cancer (continued). "Survival and response rate analysis was performed for parameters clinically relevant for metastatic colorectal cancer, such as gender, age, M0 vs. M1, number of metastatic sites, KRAS status, and primary tumor sidedness." (PMID 31307428, 2019). "In a prospective study with long-term follow-up, we analyzed circulating T cell subsets in patients with metastatic colorectal cancer (mCRC) in the context of primary tumor sidedness, KRAS status, and clinical outcome." (PMID 31307428, 2019). "A total of 779 FFPE samples from patients with metastatic colorectal cancer with valid NGS results were screened and 22 uncommon mutational profiles of KRAS, NRAS and BRAF genes were selected." (PMID 31068650, 2019). "In a prospective study, we analyzed circulating T cell subsets in patients with metastatic colorectal cancer in the context of primary tumor sidedness, KRAS status, and clinical outcome." (PMID 31307428, 2019). "The 5-fluorouracil/leucovorin plus oxaliplatin (FOLFOX) regimen is the standard first-line treatment for metastatic colorectal cancer (mCRC), however, the optimal second-line regimen for KRAS wild-type mCRC patients is still investigational." (PMID 31126331, 2019). "KRAS and NRAS mutations are identified resistance mutations to anti-epidermal growth factor receptor monoclonal antibodies in patients with metastatic colorectal cancer." (PMID 30811471, 2019). "The phase I/II Poseidon trial explored the efficacy of a combination treatment using abituzumab, an αv integrin inhibitor, and cetuximab in KRAS wild-type metastatic colorectal cancer." (PMID 31109009, 2019). "In RAS and KRAS wild-type metastatic colorectal cancer patients, miR-31-3p was used as a molecular marker to predict the response of anti-EGFR therapy." (PMID 31776419, 2019). "In a routine genotyping of KRAS mutations in metastatic colorectal cancer patients, 53 (4.7%) out of 1130 FFPE samples had KRAS mutations that were validated as artifacts due to DNA fragmentation." (PMID 31847917, 2019). "The most common mutations in KRAS, NRAS and BRAF genes were detected in less than 90 minutes in tissue biopsies and plasma samples of metastatic colorectal cancer patients." (PMID 30562355, 2018). "It is well known that activating mutations in the KRAS and NRAS genes are associated with poor response to anti-EGFR therapies in patients with metastatic colorectal cancer (mCRC)." (PMID 30344942, 2018). "Earlier studies from our laboratory show that longer TL has potential to be positive predictive biomarker of clinical outcome to anti-epidermal growth factor receptor (EGFR) monoclonal antibody therapy in patients with KRAS WT metastatic colorectal cancer." (PMID 28740573, 2017). "American Society of Clinical Oncology (ASCO) guidelines recommend that all patients with metastatic colorectal cancer (mCRC) receive KRAS testing to guide anti-EGFR monoclonal antibody treatment." (PMID 29202108, 2017). "Patients with previously untreated, KRAS exon 2 wild-type (WT) metastatic colorectal cancer (mCRC) were randomised to mFOLFOX6 plus panitumumab or bevacizumab." (PMID 28424871, 2017). "Another strategy is to combine the anti-EGFR mAb panitumumab with an anti-hepatocyte growth factor mAb rilotumumab or ganitumab, an anti-insulin-like growth factor 1 receptor (IGF-1R) mAb in metastatic colorectal cancer with wild-type KRAS (NCT00788957)." (PMID 29312320, 2017). "For e.g., it has been used for detection of mutations in KRAS, BRAF and PIK3CA in metastatic colorectal cancer." (PMID 28095454, 2017). "Anti-EGFR mAbs cetuximab and panitumumab are routinely used for the treatment of patients with KRAS-wild type metastatic colorectal cancer (mCRC)." (PMID 28032593, 2017). "As predictive markers for anti-EGFR therapy, KRAS and BRAF mutations are routinely detected in primary and metastatic colorectal cancer (CRC) cells, but seldom in circulating tumor cells (CTCs)." (PMID 29100436, 2017).
metastatic colorectal cancer (continued). "Cetuximab is approved for the treatment of metastatic colorectal cancer but its response rate in KRAS, BRAF, NRAS and PIK3CA exon 20 quadruple wild-type tumors accounts for only 41%, leaving a high percentage of non-responders." (PMID 28032592, 2017). "Patients with metastatic colorectal cancer (mCRC) harboring wild-type KRAS benefit from epidermal growth factor receptor (EGFR)-targeted therapy." (PMID 26657506, 2016). "Approximately 45% of metastatic colorectal cancer (mCRC) patients with wild-type KRAS exon 2 are resistant to cetuximab treatment." (PMID 26989027, 2016). "Subsequent studies showed that mutated KRAS acted as an in vivo oncogenic driver, as indicated by studies of anti-EGFR therapy for metastatic colorectal cancers." (PMID 27102293, 2016). "Clinical therapy for metastatic colorectal cancer (CRC) remains limited, especially when the tumor harbors a KRAS mutation." (PMID 26104296, 2015). "In 2009, treatment guidelines were updated to recommend KRAS testing at diagnosis for patients with metastatic colorectal cancer (mCRC)." (PMID 25888436, 2015). "Although they have different mechanisms of action, both drugs are routinely used in combination with first-line chemotherapy for patients with metastatic colorectal cancer (mCRC) with KRAS wild-type exon 2 tumors." (PMID 26468218, 2015). "We found that CIP2A only acts as an independent prognostic marker in patients with wild-type KRAS metastatic colorectal cancer after colorectal liver metastasectomy." (PMID 25896895, 2015). "After adjusting for other confounding factors, we found that CIP2A acts as an independent prognostic marker in patients with wild-type KRAS metastatic colorectal cancer after colorectal liver metastasectomy." (PMID 25896895, 2015). "In our analysis, the value of CIP2A as a prognostic marker was limited to patients with wild-type KRAS metastatic colorectal cancer after colorectal liver metastasectomy." (PMID 25896895, 2015). "KRAS genotyping is mandatory in metastatic colorectal cancer treatment prior to undertaking antiepidermal growth factor receptor (EGFR) monoclonal antibody therapy." (PMID 25983749, 2015). "CIP2A is an independent prognostic marker in patients with wild-type KRAS metastatic colorectal cancer after colorectal liver metastasectomy." (PMID 25896895, 2015). "Treatment and treatment results for unselected metastatic colorectal cancer patients according to BRAF/KRAS gene analyses (446 cases with BRAF analyses, 442 cases with both BRAF and KRAS analyses)." (PMID 26121270, 2015). "CIP2A is an independent prognostic marker in patients with metastatic colorectal cancer exhibiting wild-type KRAS after colorectal liver metastasectomy." (PMID 25896895, 2015). "KRAS testing is relevant for the choice of the most appropriate first-line therapy of metastatic colorectal cancer (CRC)." (PMID 24465771, 2014). "These efforts have, for instance, revealed that the expression level of the miR-31-3p allows the identification of patients with wild-type KRAS metastatic colorectal cancer responding to anti-EGFR therapy." (PMID 25243170, 2014). "This study was aimed at retrospectively evaluating the effect of statin use on outcome in KRAS mutant metastatic colorectal cancer patients (mCRC) treated with cetuximab." (PMID 25375154, 2014). "Epidermal growth factor receptor (EGFR) inhibitors are approved for treating metastatic colorectal cancer (CRC); KRAS mutation testing is recommended prior to treatment." (PMID 24788807, 2014). "Recently, a health technology assessment report has evaluated the clinical and economic profile of cetuximab in first-line metastatic colorectal cancer (mCRC) in Italy on a specific population (KRAS wt liver limited disease patients)." (PMID 24465771, 2014). "Prognosis of KRAS wild-type and mutant metastatic colorectal cancer (MCRC) patients (pts) treated with bevacizumab (BEV)-containing chemotherapy is not significantly different." (PMID 23497191, 2013).
metastatic colorectal cancer (continued). "This study aimed to assess the efficacy and safety of combination treatment with lenalidomide and cetuximab in KRAS-mutant metastatic colorectal cancer patients." (PMID 24244261, 2013). "From 2006 to 2008, several studies showed the importance of the KRAS oncogene in the treatment of metastatic colorectal cancer (mCRC) and response to anti-EGFR therapies as cetuximab or panitumumab." (PMID 24133623, 2013). "Then we analyzed the correlation between the abundance of KRAS mutations and efficacy of EGFR antibody therapy in another 35 metastatic colorectal cancer patients." (PMID 23874486, 2013). "A randomized phase II/III study of the triple combination was conducted in patients with chemorefractory metastatic colorectal cancer with a wild-type KRAS status." (PMID 23921573, 2013). "Cetuximab targets the epidermal growth factor receptor (EGFR) and is used in KRAS-wild type, metastatic colorectal cancer." (PMID 23286345, 2013). "KRAS genotype, wild-type or mutant, addresses the medical treatment of metastatic colorectal cancer (MCRC) patients (pts), consisting of triplet regimens combining chemotherapeutic drugs, or doublets plus targeted agents." (PMID 23497191, 2013). "In particular, KRAS mutations are strong predictors for clinical outcomes of EGFR-targeted treatments such as cetuximab and panitumumab in metastatic colorectal cancer (mCRC)." (PMID 23671647, 2013). "Twenty-eight regional molecular genetics centers covering all the territories and coordinating 46 laboratories are now involved in the analysis in 16,000 KRAS testing for metastatic colorectal cancer each year." (PMID 23935912, 2013). "Epidermal growth factor receptor monoclonal antibody was approved for treatment of metastatic colorectal cancer patients carrying KRAS wild type DNA." (PMID 23874486, 2013). "Panitumumab is a fully human monoclonal antibody targeting the EGFR that significantly improves progression-free survival when added to chemotherapy in patients with metastatic colorectal cancer who have wild-type (WT) KRAS tumours." (PMID 23020584, 2012). "The aim of this study is to estimate the efficacy and safety of adding cetuximab or panitumumab to oxaliplatin-based chemotherapy in the first line treatment in KRAS wild type patients with metastatic colorectal cancer (mCRC) through meta-analysis." (PMID 23226426, 2012). "Summary of KRAS data from larger studies of bevacizumab + chemotherapy in patients with metastatic colorectal cancer." (PMID 23174912, 2012). "In metastatic colorectal cancer (mCRC) a selected group of patients with wild-type KRAS respond to antibodies against the epidermal growth factor receptor (EGFR)." (PMID 23173730, 2012). "It is now recommended that KRAS gene testing is done for all patients with metastatic colorectal cancer." (PMID 24212832, 2011). "Selection of patients for epidermal growth factor receptor targeted monoclonal antibodies (MoAbs) based on tumour KRAS analysis is a major step towards tailored treatment in metastatic colorectal cancer." (PMID 21439039, 2011). "The aim of this retrospective study was to analyze objective responses, time to progression and overall survival of the patients with metastatic colorectal cancer treated with first-line systemic therapy in respect of KRAS and BRAF status." (PMID 22933967, 2011). "The currently followed practice is to offer treatment with anti EGFR therapy to patients with metastatic colorectal cancer harboring wild type KRAS only." (PMID 24212832, 2011). "In another study, genetic modulation of the let-7 miRNA binding to the KRAS 3′-untranslated region was found to correlate with survival of metastatic colorectal cancer patients who underwent salvage cetuximab-irinotecan therapy." (PMID 22102901, 2011). "Panitumumab+best supportive care (BSC) significantly improved progression-free survival (PFS) vs BSC alone in patients with chemo-refractory wild-type KRAS metastatic colorectal cancer (mCRC)." (PMID 21610704, 2011).